ACAA1 (acetyl-CoA acyltransferase 1)
Description:
Responsible for the thiolytic cleavage of straight chain 3-keto fatty acyl-CoAs (3-oxoacyl-CoAs). Plays an important role in fatty acid peroxisomal beta-oxidation. Catalyzes the cleavage of short, medium, long, and very long straight chain 3-oxoacyl-CoAs. May play a role in peroxisomal beta-oxidation step in polyunsaturated fatty acids (PUFAs) biosynthesis. Possibly regulates systemic levels of docosahexaenoic acid (DHA, C22:6n-3) through a process involving endoplasmic reticulum desaturation and elongation of alpha-linolenic acid (ALA, C18:3n-3) to form tetracosahexaenoic acid (THA, C24:6n-3), which is then beta-oxidized to DHA in peroxisomes.
Synonyms: ACAA; PTHIO; Lnc-Myd88; THIO
Tractability: Antibody: its Gene Ontology location is reachable by antibodies, with high confidence. PROTAC: ubiquitination databases record sites on it; its protein half-life has been measured.
Gene: Protein-coding gene on chromosome 3 (38,103,129 to 38,137,647, reverse strand). Ensembl gene ENSG00000060971.
Subcellular location: Peroxisome
Subcellular location (Human Protein Atlas): Peroxisomes
Pathways (Reactome):
Metabolism: Beta-oxidation of very long chain fatty acids; alpha-linolenic acid (ALA) metabolism
Protein localization: Peroxisomal protein import; TYSND1 cleaves peroxisomal proteins
Immune System: Neutrophil degranulation
Gene Ontology:
Molecular function: acetate CoA-transferase activity; long-chain fatty acyl-CoA oxidase activity; protein binding; acetyl-CoA C-acetyltransferase activity; acetyl-CoA C-acyltransferase activity; acetyl-CoA C-myristoyltransferase activity; acyltransferase activity; acyltransferase activity, transferring groups other than amino-acyl groups
Biological process: bile acid metabolic process; fatty acid beta-oxidation; very long-chain fatty acid metabolic process; alpha-linolenic acid metabolic process; fatty acid beta-oxidation using acyl-CoA oxidase; phenylacetate catabolic process
Cellular component: membrane; peroxisome; cytosol; extracellular region; peroxisomal matrix; specific granule lumen
Genetic constraint (gnomAD): Loss-of-function variants: 44 observed, 47.17 expected, observed/expected ratio (o/e) 0.93, 90% interval 0.73 to 1.2. The upper end of that interval is the gene's LOEUF score, 1.2, which puts it in group 5 of 6, group 1 being the genes least tolerant of losing a copy. Missense variants: 512 observed, 552.03 expected, observed/expected ratio (o/e) 0.93, 90% interval 0.86 to 1. Synonymous variants: 233 observed, 219.53 expected, observed/expected ratio (o/e) 1.06, 90% interval 0.95 to 1.18.
Homologues: Orthologues: chimpanzee ACAA1 (100% identical), macaque ACAA1 (99% identical), dog ACAA1 (92% identical), guinea pig Acaa1 (90% identical), pig ACAA1 (88% identical), rat Acaa1b (87% identical), rat Acaa1a (87% identical), mouse Acaa1b (86% identical), mouse Acaa1a (86% identical), rabbit ACAA1 (82% identical), tropical clawed frog acaa1 (75% identical), zebrafish acaa1 (72% identical). Paralogues in human: ACAT2 (39% identical), ACAA2 (37% identical), HADHB (35% identical), ACAT1 (31% identical).
Diseases named in the same sentence as ACAA1 in open-access papers:
ACAA1 is named in the same sentence as 59 diseases in open-access papers, as found by Europe PMC text mining. Sharing a sentence is not in itself a finding about the gene and the disease. The quoted sentences say what the papers report.
breast carcinoma (4 papers, 2020 to 2025). "Reduced ACAA1 expression has been linked to enhanced tumour progression and poorer survival in cancers including hepatocellular carcinoma, breast cancer, and non-small cell lung cancer." (PMID 41277949, 2025). "In breast cancer, ACAA1 inhibition has been shown to restrain the proliferation of cancer cells." (PMID 41262516, 2025).
gastric cancer (4 papers, 2012 to 2024). A primary or metastatic malignant neoplasm involving the stomach. "Increased expressions of PPARA1, ACAA1, FABP1, and FABP2 were detected in SNU-478 ampullary cancer cells compared to pancreatic cancer cells (Pan1 and MIA-Pan2) and gastric cancer cells (AGS) by qPCR." (PMID 33390794, 2021). "Although a role for ACAA1 in gastric cancer has not been clarified, researchers observed that ACAA1 down-regulation inhibited the proliferation of triple-negative breast cancer cells and enhanced their response to CDK4/6 inhibitors." (PMID 38406279, 2024).
non-small cell lung carcinoma (4 papers, 2020 to 2025). A group of at least three distinct histological types of lung cancer, including non-small cell squamous cell carcinoma, adenocarcinoma, and large cell carcinoma. "ACAA1 may be a marker for non-small cell lung cancer (NSCLC) diagnosis and prognosis, and may provide new insights for NSCLC treatment." (PMID 33903282, 2021).
fatty liver (3 papers, 2014 to 2025). "Thus, the increased expression of Acacb in HF-fed Nrf2−/− livers, coupled with the exaggerated loss of Cpt1a and Acaa1 expression, may contribute to the increased hepatic steatosis in these animals." (PMID 24958099, 2014). "Collectively, the results suggest that ACSL1, ACSL5, EHHADH, and ACAA1 play an important role in the development of fatty liver disease in dairy goats." (PMID 40723475, 2025). "The results showed that the four genes (ACSL1, ACSL5, EHHADH, and ACAA1) were significantly upregulated in the hepatic tissues of dairy goats with fatty liver." (PMID 40723475, 2025). "Notably, by observing the overlap among these three sub-networks, we found that proteins with downregulated ubiquitination—such as ACSL1, ACSL5, EHHADH, and ACAA1—were transcriptionally upregulated in dairy goats with fatty liver." (PMID 40723475, 2025). "Indeed, we observed significantly elevated gene expression of ACSL1, ACSL5, EHHADH, and ACAA1 in the hepatic tissues of periparturient goats affected by fatty liver disease." (PMID 40723475, 2025). "We speculate that the altered ubiquitination of ACSL1, ACSL5, EHHADH, and ACAA1 contributes to their increased hepatic protein levels and abnormal subcellular localization in dairy goats with fatty liver." (PMID 40723475, 2025).
hepatocellular carcinoma (3 papers, 2023 to 2025). A malignant tumor that arises from hepatocytes. "Some of the genes in these pathways include ALAS1, ACAA1, and ACOX2 which are negatively correlated with recurrence-free survival in patients with hepatitis B-related (HBV) hepatocellular carcinoma (HCC)." (PMID 36768794, 2023).
lung carcinoma (3 papers, 2020 to 2025). "As our research interest is focused on lung cancer, we re-analyzed ACAA1 expression in tumor tissue and adjacent normal tissue using a GEO dataset (GSD 3837)." (PMID 33194642, 2020). "KRAS mutation is the second most prevalent mutation in lung cancer, and we observed that KRAS regulated the mRNA of ACAA1." (PMID 33194642, 2020). "In various other cancer cell lines besides pancreatic cancer, including OVCAR-8 (ovarian cancer), A549 (lung cancer), SNU-449 (liver cancer), HCT-8 (colon cancer), and PC-3 (prostate cancer), ACAA1 knockdown similarly reduced basal respiration and ATP production." (PMID 40848971, 2025). "Notably, considering the importance of HSD17B4 and ACAA1 in peroxisomal β-oxidation of very long fatty acids, the dysfunction of the process in NSCLC was indicated, consistent with the anti-tumor function of β-oxidation in lung cancer in a previous study." (PMID 32265992, 2020).
pancreatic cancer (3 papers, 2021 to 2025). "The average H-score of ACAA1 in normal tissue was 17, whereas in pancreatic cancer tissue it was 31.2, indicating a 1.83-fold increase compared to normal tissue." (PMID 40848971, 2025). "To examine changes in ACAA1 expression during pancreatic cancer development, we analyzed its expression at key stages of tumor progression in wild-type and KPC mice." (PMID 40848971, 2025). "ACAA1 has been reported to have higher expression in pancreatic cancer than in normal tissue." (PMID 41155168, 2025). "To explore the impact of FAO activity in peroxisomes on pancreatic cancer, we compared the expression of ACAA1 and peroxisomal acyl-coenzyme A oxidase (ACOX1), the key proteins involved in FAO within peroxisomes, using commercially available pancreatic cancer tissue microarrays." (PMID 40848971, 2025). "To determine whether cancer cells rely on peroxisomal FAO, we performed ACAA1 knockdown using sequences from two shRNAs in two pancreatic cancer cell lines." (PMID 40848971, 2025). "The expression of ACAA1 and ACOX1, target proteins of peroxisomal FAO, was significantly increased in pancreatic cancer tissue." (PMID 40848971, 2025).
asthma (2 papers, 2011 to 2025). "Genetic evidence highlights its immuno-modulatory potential, as demonstrated by the ACAA1 SNP (rs156265) that modifies endotoxin-induced childhood asthma risk." (PMID 41277949, 2025). "The ACAA1 SNP that modified the association between endotoxin and asthma risk is found less than 10 kb from MYD88, in a region that may regulate MYD88 transcription." (PMID 22151743, 2011). "The results of our study show modification of the association between endotoxin exposure and asthma by a genetic polymorphism in ACAA1, demonstrating that higher home endotoxin levels appear to confer protection against asthma only in those individuals with this SNP (rs156265)." (PMID 22151743, 2011). "Our findings suggest that protective effects of endotoxin exposure on asthma may vary depending upon the presence or absence of a polymorphism in ACAA1." (PMID 22151743, 2011).
cognitive decline (2 papers, 2021 to 2025). "A recently identified missense variant in ACAA1 was shown to impair lysosomal function, thereby aggravating amyloid-β pathology and accelerating cognitive decline in early-onset AD." (PMID 41593936, 2025). "In addition, a recent study discovered a novel missense variant in ACAA1, linked to early-onset AD, impaired lysosomal function, and the worsening of amyloid-β pathology and cognitive decline." (PMID 41593936, 2025).
colorectal cancer (2 papers, 2024 to 2025). A primary or metastatic malignant neoplasm that affects the colon or rectum. "Our computational study confirmed that colorectal cancer had also been associated with the upregulation of 16 genes, such as MMP1, and the downregulation of one gene (ACAA1)." (PMID 38528462, 2024).
glioma (2 papers, 2020 to 2021). A benign or malignant brain and spinal cord tumor that arises from glial cells (astrocytes, oligodendrocytes, ependymal cells). "In order to gain an understanding of the biological consequences underlying the dysfunction of ACAA1 enzyme at the molecular and cellular levels, we performed cellular assays using the U251 glioma cell line and the human microglia (HM) cell line overexpressing ACAA1 WT and p.N299S, respectively." (PMID 34465723, 2021). "It is suggested that targeted therapy for ACAA1 in IDH mutation gliomas may be a new promising and effective target for gliomas." (PMID 32280672, 2020).
triple-negative breast carcinoma (2 papers, 2024). An invasive breast carcinoma which is negative for expression of estrogen receptor (ER), progesterone receptor (PR), and human epidermal growth factor receptor 2 (HER2). "The ACAA1 gene was revealed to be highly expressed in triple-negative breast cancer cells, and inhibiting the ACAA1 gene decreased the proliferation of triple-negative breast cancer cells." (PMID 38756449, 2024).
ampullary adenocarcinomas (1 paper, 2021). "Increased expressions of ACAA1 (acetyl-CoA acyltransferase 1), FABP1 (fatty acid-binding protein 1), PPARA, and FABP2 genes were seen in ampullary adenocarcinomas compared to pancreatic adenocarcinomas." (PMID 33390794, 2021).
childhood asthma (1 paper, 2020). "In addition, as one of the innate immunity genes, the single nucleotide polymorphisms (SNPs) of ACAA1 have been reported to be associated with pathogenesis of childhood asthma and the protective effects of its exposure to endotoxin." (PMID 32265992, 2020).
Cognitive impairment (1 paper, 2021). Abnormal cognition is characterized by deficits in thinking, reasoning, or remembering. "It will be rewarding to perform a prospective drug study with ACAA1 as a valid druggable target for improving the pathological characteristics and cognitive impairment symptoms in AD patients with deficiency of ACAA1 enzyme activity and impaired VLCFA β-oxidation." (PMID 34465723, 2021). "Overexpression of ACAA1 p.N299S has been shown to contribute to AD by disturbing its enzymatic activity, inhibiting the lysosome system, and aggravating the Aβ pathology and neuronal loss, which finally caused a cognitive impairment in a murine model of AD." (PMID 34465723, 2021). "Further in vitro and in vivo evidence showed that ACAA1 p.N299S contributes to AD by disturbing its enzymatic activity, impairing lysosomal function, and aggravating the Aβ pathology and neuronal loss, which finally caused cognitive impairment in a murine model." (PMID 34465723, 2021).
diabetes (1 paper, 2015). "In addition, it uncovers biomarker genes such as ACAA1 and HSD17b4 which could be further probed in future studies of pre-diabetes and T2D." (PMID 25784953, 2015).
dyslipidemia (1 paper, 2015). "Acetyl-CoA acyltransferase 1 is involved in the regulation of genes encoding cholesterol biosynthesis enzymes in the liver, suggesting that the peroxisome could be a promising candidate for the correction of cholesterol imbalance in dyslipidemia." (PMID 26467524, 2015).
graft versus host disease (1 paper, 2025). An immune system disorder that occurs after allogeneic hematopoietic stem cell transplant and is a reaction of donor immune cells against host tissues. "KEGG analysis showed that high ACAA1 expression correlates with signalling pathways such as allograft rejection, graft-versus-host disease, staphylococcus aureus infection, and viral protein interaction." (PMID 41277949, 2025).
heart failure (1 paper, 2024). Inability of the heart to pump blood at an adequate rate to meet tissue metabolic requirements. "Single enzyme defects in peroxisomal α- and β-oxidation, including the PTS2-proteins, PHYH, and ACAA1, cause toxic levels of BC/VLCFAs leading to heart failure." (PMID 38365851, 2024).
invasive ductal carcinoma (1 paper, 2020). "The feature plots and spatial feature plots were utilized to illustrate the distribution and expression of CIRBP, FAM110B, ACAA1, ACAT1, and DHCR7, showing that these key genes were highly expressed in the invasive ductal carcinoma tissue (cluster 2, 5, 8)." (PMID 32984314, 2020).
lung adenocarcinoma (1 paper, 2020). A carcinoma that arises from the lung and is characterized by the presence of malignant glandular epithelial cells. "To analyze how oncogenic KRAS regulates ACAA1 expression and the related upstream signaling pathway, we used lung adenocarcinoma cell line H1944, which harbors KRASG13D mutation." (PMID 33194642, 2020).
mastitis (1 paper, 2021). Inflammation of breast tissue during lactation or postpartum due to an obstructed duct or infection.
melanoma (1 paper, 2025). A malignant, usually aggressive tumor composed of atypical, neoplastic melanocytes. "H-scores calculated with Inform software (version 2.6.0) indicated median ACAA1 scores of 45.3 in normal skin and 166.1 in melanoma tissue." (PMID 41155168, 2025). "After siRNA knockdown of CAC or ACAA1 in UACC-257 melanoma cells, OCR analysis revealed a significant reduction in basal respiration and ATP production compared to the control group." (PMID 41155168, 2025). "We demonstrated that melanoma tumor regrowth by Dabrafenib or Dacarbazine treatment is completely reversed by inhibiting FAO using KN510713 (targeting CAC and ACAA1/2)." (PMID 41155168, 2025).
nasopharyngeal carcinoma (1 paper, 2025). A carcinoma arising from the nasopharyngeal epithelium. "Here, we observed a marked downregulation of ACAA1 in nasopharyngeal carcinoma (NPC), which displayed an inverse correlation with the expression genes coded by Epstein-Barr virus (EBV)." (PMID 41277949, 2025).
Obesity (1 paper, 2026). Accumulation of substantial excess body fat. "While discovery datasets showed high diagnostic potential, ADI1 exhibited more variable performance in obesity external validation compared to the robust consistency of ACAA1." (PMID 41801960, 2026).
Zellweger syndrome (1 paper, 2013). "Loss of Tysnd1 interferes with the peroxisomal localization of Acaa1, Phyh, and Agps, which might cause the mild Zellweger syndrome spectrum-resembling phenotypes." (PMID 23459139, 2013).